TNF (tumor necrosis factor)
Diseases named in the same sentence as TNF in open-access papers (continued):
Sharing a sentence is not in itself a finding about the gene and the disease.
Sepsis (continued). "In this study, we observed the severe inflammatory damage with increase of TNF-α, IL-6, and IL-10 in the ileum from the CLP-induced sepsis model, which was consistent with the previous study." (PMID 33376482, 2020). "Upregulation of miR-181 during sepsis is known to enhance TNF-α mRNA degradation and inhibit LPS-induced inflammation, as indicated by the reduced IL-8 and TNF-α concentrations." (PMID 33182754, 2020). "During sepsis, HIF-1α, stimulated by LPS, activates the generation of inflammatory cytokines (including TNF-α, IL-1β and IL-6) and proapoptotic proteins, leading to inflammation and apoptosis." (PMID 32353952, 2020). "Accordingly, in contrast with inflammatory cytokines such as IL-1β, IL-6, TNF-α, and IFN-γ, elevation of IL-18 has levels been reported to be characteristic of AOSD and, thus, potentially useful for differentiating AOSD from sepsis." (PMID 32381117, 2020). "Significant differences were observed in the expression of the pro-inflammatory cytokine genes IL-2, IL-6, TNF, and IFN-γ and the anti-inflammatory cytokine genes IL-4 and IL-10 between sepsis patients and healthy controls." (PMID 32922168, 2020). "In sepsis, there are two major cytokines responsible for LVEF decrease, known as tumor necrosis factor (TNF) and IL-1β and the result of LVEF drop is cardiac remodeling with ventricular dilatation." (PMID 33198152, 2020). "A cytokine array found that the QX1 formula attenuated sepsis-induced upregulated levels of serum IFN-γ, IL-1β, IL-3, IL-6, IL-17, IL-4, IL-10, and TNF-α." (PMID 32908632, 2020). "Enbrel is a TNFα inhibitor FDA approved to treat arthritis and plaque psoriasis, with adverse interactions including headache, infection, rhinitis, and sepsis." (PMID 32365960, 2020). "The serum levels of TNF-α and TREM were significantly lower in the rats from the sepsis + cefazolin + etanercept group than in those from the sepsis + cefazolin group." (PMID 32348434, 2020). "The expression levels of TNF-α, IL-6, and IL-1β were significantly increased inthe CLP group compared with the sham group, indicating that sepsis promotedinflammation." (PMID 32578720, 2020). "Tumor necrosis factor (TNF) may beinvolved in preventing PDH activity in the skeletalmuscles of rats with chronic abdominal sepsis.Blood or serum lactate concentration during sepsis isregarded as the most important indicator of morbidityand mortality during sepsis." (PMID 31376317, 2020). "IL-13 could exert a protective effect against sepsis by suppressing local inflammation, as shown by the previous study that antibody-mediated inhibition of IL-13 in the sepsis model increased macrophage inflammatory protein-2, macrophage inflammatory protein-1α and TNF-α levels." (PMID 33679715, 2020). "After in vitro culture of monocytes from sepsis patients, PGE2 diminished CD14+CD16+ monocytes after 24 h, reduced TNF‐α production, but enhanced anti‐inflammatory IL‐10 production." (PMID 32700336, 2020). "In a rat model of endotoxin induced sepsis, pretreatment with capsaicin increases anti-inflammatory cytokine IL-10 levels, and attenuation of CGRP, TNF, and interleukin 6 (IL-6) cytokines." (PMID 33193423, 2020). "It was suggested that the serum levels of IL-6, IL-8, and TNF-α were significantly higher whereas those of IL-10, IL-13, and TGF-β were significantly lower in the sepsis group than those in the sham group." (PMID 31830649, 2020). "Intraperitoneal injection of asiaticoside, a triterpenoid saponin, in CLP-induced mice, reduced the serum levels of IL-6 and TNF-α, the expression of COX-2 and iNOS in lung tissue, and the severity of lung injury due to sepsis." (PMID 33193799, 2020). "We then examined the serum levels of inflammatory cytokine TNF-α, IL-6, IL-1β, and IL-10, and the clinical markers of acute systemic inflammation MCP-1 and CRP by ELISA in LPS-induced sepsis model." (PMID 32457606, 2020).
Sepsis (continued). "Specifically, TNF-α and MIP-2 are primary cytokines known to trigger a variety of clinical manifestations of LPS-induced sepsis, whereas IL-6 levels correlate to a poor outcome and multiple organ failure in septic patients." (PMID 32353952, 2020). "The levels of TNF-α, TREM, and MDA in serum and kidney samples were significantly higher in rats from sepsis group than in rats from control group (p < 0.05)." (PMID 32348434, 2020). "The detection of inflammatory mediators of each group showed that LPS significantly increased the levels of TNF-α, IL-6, IL-1β, and MCP-1, and decreased the level of IL-10, consistent with those results discovered in mice with sepsis-induced kidney injury." (PMID 33197894, 2020). "The levels of pro-inflammatory cytokines, including tumor necrosis factor (TNF)-α, IL-1β, IL-6, and MCP-1, have been observed to increase in the myocardium in response to sepsis." (PMID 32256344, 2020). "Following sepsis induction by CLP, the pro-inflammatory cytokines, IL-1β, IL-6, tumor necrosis factor (TNF)-α, and monocyte chemoattractant protein (MCP)-1, showed a marked increase." (PMID 32943679, 2020). "While TNF and LCN2 are dramatically upregulated in both ischemic and septic AKI, KIM-1 is induced primarily in ischemic injury and ICAM-1 in sepsis only." (PMID 32257978, 2020). "Zinc administration protects against TNF‐induced lethal SIRS, as well as in other models of SIRS, sepsis, and infection." (PMID 32914580, 2020). "Further, the rats treated with cefazolin and etanercept demonstrated significantly reduced levels of serum TNF-α, CRP, TREM, and MDA as compared with those from the sepsis group (p < 0.05)." (PMID 32348434, 2020). "In sepsis, TNF-α is related to organ dysfunction and increased lethality, while MIF upregulate TLR-4 and TNF-α in macrophages." (PMID 33110395, 2020). "Pretreatment of rats with cefazolin resulted in a significant reduction in the serum levels of TNF-α, CRP, and TREM as compared with the rats from the sepsis group (p < 0.05)." (PMID 32348434, 2020). "Analysis of the kidney tissue samples revealed the significantly higher levels of TNF-α, TREM, and MDA in the sepsis group than those in the control group (p < 0.05)." (PMID 32348434, 2020). "The activity of MPO, the levels of pro-inflammatory cytokines, including TNF-α and IL-6, in the intestine, the activity of DAO and the content of MDA in the serum in the sham, sepsis and sesamin (50 μM) + sepsis groups were examined." (PMID 32893702, 2020). "In both groups (isoflurane and Propofol), exposure to cecal ligation and puncture (CLP)/sepsis-inflammation led to increased fluid requirements, lower MAP at 8 h, development of a base deficit, and increased interleukins (IL-6, IL-1β, and TNF-α) at 8 h." (PMID 33392215, 2020). "In MRSA-induced sepsis mouse model, XBJ decreased the secretion of IL-6, TNF-α, MCP-1, MIP-2, and IL-10 in sera and alleviated lung, liver, and kidney damage." (PMID 32153410, 2020). "An oral administration of the ethyl acetate extract (0.78–1.32 mg/kg) improved the survival rate of endotoxemic mice and reduced the serum levels of NO, TNF-α, and macrophage inflammatory protein (MIP)-2, all of which play proinflammatory roles in sepsis." (PMID 33193799, 2020). "In cardiomyocytes of mice with LPS-induced sepsis, upregulation of lncRNA HOTAIR promotes TNF-α production by activating NF-κB, involving the p-NF-κB p65 subunit." (PMID 33024135, 2020). "Results showed that TNF, HSPA1A, HSPA1B, TREM1, SOD2 and MIF genes related to sepsis correspond to m6A-cis-eQTLs." (PMID 32174955, 2020). "Levels of inflammatory markers like tumor necrosis factor-alpha (TNF-α), interleukin-1-beta (IL-1β) and, interleukin-6 (IL-6) as well as VEGF, a specific sepsis marker in plasma, were quantified." (PMID 33371296, 2020).
Sepsis (continued). "Our primary goal was to directly compare levels of 6 inflammatory cytokines commonly associated with cytokine storm (IL-1β, IL-1RA, IL-6, IL-8, IL-18, and TNF-α) between severe COVID-19 patients and patients with ARDS or sepsis." (PMID 32706339, 2020). "We also observed a significantly lower levels of serum TNF-α and TREM in the rats from sepsis + cefazolin + etanercept group than in those from sepsis + cefazolin group." (PMID 32348434, 2020). "The reduced TNF-α and IL-6 levels were correlated with the increased IL-10 and TGF-β levels in sera of CLP-induced sepsis mice treated with rSj-Cys compared with the CLP group without treatment." (PMID 32423469, 2020). "The most frequent TNF-α -308G/A, -238G/A and -376G/A haplotypes were as follows: GGG (85.5%), AGG (11.21%), GAG (1.24%) in sepsis study group and GGG (87.28%), AGG (9.42%), GAG (1.5%) in controls (p > 0.05)." (PMID 32171247, 2020). "Inhibition of calcium/calmodulin-dependent protein kinase Iα increased survival rate by reducing systemic concentrations of IL-10, IL-6, TNF-α, and HMGB1 in a CLP model of sepsis." (PMID 30848296, 2019). "The α7 nAChR partial agonist GTS-21 reduces secretion of pro-inflammatory cytokines including interleukin-6 (IL6) and tumor-necrosis factor (TNF) in models of endotoxemia and sepsis, and its anti-inflammatory effects are widely ascribed to α7 nAChR activation." (PMID 30947238, 2019). "We found that the mRNA expressions of TNF-α, IL-1β, and IL-6 were upregulated in MLN DCs and those of IL-1β and IL-6 were augmented in SP DCs by sepsis." (PMID 31323786, 2019). "LPS-induced sepsis is less severe when injection at ZT10 than at ZT12, coinciding with a decrease in pro-inflammatory cytokines TNF-α, IL-6, and CXCL1 at ZT12, and increase in the anti-inflammatory cytokine IL-10." (PMID 31470863, 2019). "In lipopolysaccharide (LPS)-induced sepsis, lung expression of 5-HT7 receptors increases in parallel to the increased expression of TNF-α, IL-1β, and NF-κB." (PMID 31892309, 2019). "More than 170 biomarkers have been identified for the assessment of sepsis, including PCT, CRP, TNF-α/IL-6, MCP-1, miRNA, and other indicators." (PMID 31671729, 2019). "GTS-21 (also known as DMBX-anabaseine) inhibits pro-inflammatory cytokines like TNF, IL-1β, IL6 and HMGB1 and improves survival in murine endotoxemia and sepsis models." (PMID 30947238, 2019). "Here, we demonstrated that THOP1-/- mice have slightly better survival and behavior performance seven days after polymicrobial sepsis induction, with slightly lower expression of TLR4 and TNF-α in dorsal hippocampus." (PMID 31431000, 2019). "Comparison of molecules between the control and sepsis groups revealed statistically significant differences, except for IFN-α, IL-1RA, IL-1β, IL-2, IL-6, IL-7, IL-15, LIF, GM-CSF, TNF-α, CCL4, CCL5, and CXCL12." (PMID 31583025, 2019). "Increased survival in LPS, TNF-α, and CLP sepsis, rescued from lethality in E. coli infusion, attenuated cardiac injury and dysfunction in sepsis." (PMID 31736963, 2019). "At 72 HPI, sepsis appeared to have progressed, with an increase in serum IFNγ, IL1β, IL10, and TNFα." (PMID 31121001, 2019). "In a sepsis mice model, LPS can induce the upregulation of HOTAIR in cardiomyocytes, in line with increased NF-κB activation and TNF-α production, which is reversed by HOTAIR silence." (PMID 31711545, 2019). "High levels of circulating pro-inflammatory cytokines, such as TNFα, IL-1, and interleukin-6 (IL-6), were cited as evidence of SIRS in both septic human patients and laboratory animals with induced sepsis." (PMID 30931316, 2019). "During inflammation and sepsis, plasma C-reactive protein (CRP), IL-6, IL-1β, and TNF-α levels in the circulatory system are increased." (PMID 31835381, 2019).
Sepsis (continued). "Then, Caco-2 monolayers were utilized to further investigate the protective effect of the EcN supernatant (EcNsup) on the barrier dysfunction induced by TNF-α and IFN-γ in vitro; the plasma level of both the cytokines increased significantly during sepsis." (PMID 31354386, 2019). "EP downregulated the expression of multiple proinflammatory proteins, including IL-1β, TNF-α, and HMGB1 in animal experiments of endotoxemia and sepsis." (PMID 31933629, 2019). "We then measured the levels of proinflammatory cytokines (IL-6 and TNF), histones, and C5a in plasma from TLR3−/−, TLR9−/−, and Wt after inducing polymicrobial sepsis by CLP." (PMID 30364002, 2018). "Previous in vivo and in vitro studies have demonstrated that HO-1 reduces the production of proinflammatory cytokines, including TNF-α and IL-6, and inhibits the activation of NF-κB and MAPK signaling during sepsis." (PMID 30533176, 2018). "Co-culture with ILC2 markedly reduced MLEC death induced by LPS and TNFα, suggesting a direct protective effect of ILC2 on MLEC in sepsis." (PMID 29511181, 2018). "PKCδ inhibition significantly reduced TNF-α-mediated hyperpermeability and TEER decrease in vitro in activated HBMVEC and rat brain in vivo 24 h after CLP induced sepsis." (PMID 30400800, 2018). "In the previous series of studies, we found that the content of TNF-α, NO, NOS, and other inflammatory factors of liver or intestine tissue was significantly increased in sepsis and abdominal adhesion rats." (PMID 30402132, 2018). "Plasma cytokine levels of IL-1β, TNF-α, IL-6, and MCP-1 were markedly increased in patients with sepsis compared to those in healthy control subjects." (PMID 30337925, 2018). "In previous studies on HMGB1, TNF-α and IL-6 were often used for reference and comparison with HMGB1, especially in studies on sepsis." (PMID 30157804, 2018). "Inflammatory cytokines TNFα and IL6, determined from the renal venous blood, were elevated in sepsis." (PMID 30343340, 2018). "All these studies show that both type-1 and type-2 diabetic animals have exacerbated hyperglycemia, and production of both pro- (TNF, IL1, IL6, MCP1) and anti-inflammatory (IL10) cytokines in experimental sepsis." (PMID 29780390, 2018). "Our study showed that serum levels of tenascin-C in patients with sepsis were significantly positively correlated with serum inflammatory factors, CRP, IL-6 and TNF-α." (PMID 30442110, 2018). "For example, IL-6, TNF-α, and HMGB1 levels are significantly higher in sepsis patients than in patients with other diseases or healthy people." (PMID 29780830, 2018). "On the other hand, in CLP-induced sepsis model in HSP70.1/3 knockout mice NF-κB binding/activation, TNFα and IL-6 in lung tissue as well as mortality were increased after sepsis." (PMID 29728738, 2018). "We aimed to investigate if reductions in the plasma concentrations of TNF-α, interleukin (IL)-6 and IL-10, and of the IL-6 rate of change at 24 h after ICU admission were survival predictors for Vietnamese patients with sepsis and septic shock." (PMID 30400775, 2018). "MCs increases the recruitment of neutrophils through release of several inflammatory mediators that includes tumor necrosis factor (TNF), histamine and leukotrienes, and reduced animal survival in lipopolysaccharide (LPS)-induced sepsis rodent model." (PMID 30719003, 2018). "The suppression of HBP expression by heparin injection after the establishment of sepsis-induced AKI resulted in a reduction in renal injury severity accompanied with a significant repression of M1 macrophage activation and expression of TNF-α and IL-6." (PMID 29723248, 2018). "We have reported a pivotal role for Nuclear Factors of Activated T cells (NFATc3) in regulating macrophage phenotype during sepsis induced ALI and subsequent studies demonstrate that NFATc3 transcriptionally regulates macrophage CCR2 and TNFα gene expression." (PMID 29535830, 2018).
Sepsis (continued). "Firstly, the current study found that sepsis rats exhibited increased expressions of D-lactic acid, DAO, bacterial translocation, MDA, TNF-α, IL-6, and IL-10, in addition to decreased SOD activity." (PMID 30340459, 2018). "Patients with ACLF demonstrated a sepsis like immune paralysis as ex vivo secretion of TNF-α after stimulation with LPS was reduced in patients with ACLF and severe sepsis when compared to patients with compensated cirrhosis." (PMID 30020985, 2018). "A marked increase of TNF-α and IL-6 secretion was observed in the CLP sepsis group compared with the sham group (p < 0.05)." (PMID 28694565, 2017). "They compared TNF-α production and CD14 expression on monocytes among patients with severe sepsis, septic shock or cardiogenic shock as well as in healthy volunteers." (PMID 28274246, 2017). "This study documents the endogenous production of IL-6, TNF-α and IL-10 in rats with cecal ligation and puncture (CLP) induced sepsis on conscious animals with intermittent blood sampling in the individual rat during a 72-h period." (PMID 29204105, 2017). "TNF is a strong inductor of the acute phase response in SIRS and is the most extensively studied cytokine in sepsis." (PMID 28261486, 2017). "Our findings revealed that T. gondii infection robustly induces long-lived IFN-γ- and TNF-α-producing CD4+ and CD8+ T cells that are maintained, reprogrammed and amplified to act against a secondary challenge of sepsis." (PMID 28439500, 2017). "Of these cytokines, tumor necrosis factor-α (TNF-α) and interleukin-1β (IL-1β), which are produced excessively at the early stages of sepsis, have been found to depress cardiac function synergistically." (PMID 28270914, 2017). "In German adult patients with Candida sepsis, the heterozygotic status in TLR2 2258 G>A SNP was correlated with altered cytokine release, including increased plasma concentrations of TNF-α and decreased levels of IFN-γ and IL8." (PMID 28118851, 2017). "Granzyme K promotes a pro-inflammatory response with production of TNF-α, IL6 and monocyte chemotactic protein 1, is elevated sepsis, and also is released against activated T cells in multiple sclerosis." (PMID 28850071, 2017). "As shown inFigure 3A, TNFα levels increased in bothwild-type and S100A9 knockout mice during early sepsis, but were significantly higherin wild-type mice." (PMID 29204146, 2017). "In the cecal ligation and puncture (CLP) model of sepsis, PPAR-γ agonist ameliorates systemic inflammation by decreasing plasma levels of TNF-α and IL-6 via inhibition of nuclear factor kappa B (NF-κB)." (PMID 28845215, 2017). "Additionally, knockout of IL-6 or TNF-α could not affect the loss of body weight during sepsis in mice." (PMID 28661460, 2017). "In the previous study, the levels of TNF-α and IL-6 in the plasma were also substantially increased in CLP-induced sepsis." (PMID 28694565, 2017). "As evidenced by the plasma level of TNF‐α and gene expression of IL‐1β and TNF‐α in the heart, inflammation was developed in the sepsis group." (PMID 28684640, 2017). "The therapeutic effects of rSj-Cys treatment were associated with the significant reduction of pro-inflammatory cytokines (TNF-α, IL-1β and IL-6) and boost of IL-10 and TGF-β1 cytokines in sera of mice with sepsis." (PMID 28482922, 2017). "With respect to the IL-6 and TNF-α, hemodynamic, and biochemical responses CLP model is the most comparable to human sepsis." (PMID 28976923, 2017). "Moreover, the negative correlation between LiMAx, CT-pro-ET-1 and TNF-α suggests an interaction between liver failure and these peptides, which leads to the conclusion that ET-1 and TNF-α may have an important impact on the development of liver failure in sepsis." (PMID 28542386, 2017). "However, TNF-α rs361525 and sepsis risk were positively correlated in the PB, but not HB group." (PMID 29340067, 2017).